BCR (BCR activator of RhoGEF and GTPase)
Diseases named in the same sentence as BCR in open-access papers (continued):
Sharing a sentence is not in itself a finding about the gene and the disease.
chronic myeloid leukemia (continued). "BCR-ABL fusion tyrosine kinase (FTK) has long been linked to HRR activation and the emergence of therapy resistance in Chronic Myelogenous Leukaemia (CML); a scenario similar to MM." (PMID 38943005, 2024). "The oncogene BCR::ABL1 is a key player in chronic myeloid leukemia (CML), as well as in acute lymphoblastic leukemia (ALL), collectively known as Philadelphia chromosome-positive (Ph+) neoplasms." (PMID 38906962, 2024). "Chronic myelogenous leukemia (CML) is a malignancy from bone marrow myeloid stem cells mainly driven by the fusion gene BCR-ABL." (PMID 37588191, 2024). "Targeted inhibition of oncogenic protein BCR::ABL1 with tyrosine kinase inhibitors (TKIs) is a front-line therapy in patients with chronic myeloid leukemia (CML) and Ph + acute lymphoblastic leukemia." (PMID 39182842, 2024). "For instance, the BCR-ABL fusion transcript is a defining marker for chronic myeloid leukemia (CML), while EML4-ALK fusions are found in a subset of non-small-cell lung cancers." (PMID 39857631, 2024). "We used the library to screen K-562 cells, a BCR-ABL chronic myeloid leukemia cell line commonly used for functional genomics, and collecting samples at 7, 14, and 21 days." (PMID 38678031, 2024). "Both classifications continued to require a 20% blast requirement for AML with BCR:ABL1 fusion to prevent diagnostic intersection with the parent disease, chronic myeloid leukemia (CML)." (PMID 39199685, 2024). "In one study, the knockdown of Fyn kinase via pharmacological inhibition or siRNA resensitized a BCR-ABL inhibitor imatinib-resistant chronic granulocytic leukaemia (CML) cell line (IM-R cells) to imatinib." (PMID 39697541, 2024). "The latest World Health Organization (WHO) classified MPNs into chronic myeloid leukemia (CML) BCR::ABL1+, polycythemia vera (PV), essential thrombocythemia (ET), and primary myelofibrosis (PMF)." (PMID 36873934, 2023). "The BCR-ABL fusion gene of childhood and adult ALL have a different molecular basis, with the BCR-ABL fusion gene in adult ALL of the “p210” subtype resembling that found in chronic myeloid leukemia (CML), whereas the childhood subtype is mainly “p190”." (PMID 37685286, 2023). "The therapeutic armamentarium of chronic myeloid leukemia (CML) has greatly improved after small molecule tyrosine kinase inhibitors (TKIs) targeting BCR::ABL1 became available." (PMID 37033642, 2023). "Chronic myeloid leukemia (CML) is a myeloproliferative neoplasm caused by a BCR-ABL fusion gene." (PMID 37124196, 2023). "In chronic myeloid leukemia (CML), the hematopoietic neoplasm is predominantly caused by the formation of the BCR::ABL1 kinase." (PMID 37384296, 2023). "Tyrosine kinase inhibitors (TKI) are effective target-specific inhibitors of the constitutively active BCR::ABL1 oncoprotein characterizing chronic myeloid leukemia (CML)." (PMID 37875583, 2023). "Chronic myeloid leukemia (CML), caused by constitutively active BCR::ABL1 fusion tyrosine kinase, has served as a paradigm for the successful application of molecularly targeted cancer therapy." (PMID 37696829, 2023). "Reverse transcriptases (RT) play a crucial role in BCR::ABL1 fusion transcript monitoring of chronic myeloid leukemia (CML)." (PMID 37568730, 2023). "Imatinib, originally designed as a kinase inhibitor to target the BCR-ABL fusion protein in chronic myeloid leukemia, was later found to also activate the serotonin 4 (5-HT4) receptor, a GPCR associated with gastrointestinal function." (PMID 37888725, 2023). "We observed that among tested cell lines, K-562, a Philadelphia (Ph) chromosome-positive (BCR-ABL-positive) leukemia cell line derived from chronic myeloid leukemia (CML) in blast crisis, was the most resistant toward the tested compounds." (PMID 37514177, 2023). "In chronic myelogenous leukemia with BCR::ABL1 fusion, the f-circRNA circBA9.3 was shown to promote proliferation and repress apoptosis by improving BCR::ABL1 transcript translation or preventing its degradation." (PMID 36585787, 2023).
chronic myeloid leukemia (continued). "Response to tyrosine kinase inhibitor (TKI) therapy in patients with chronic myeloid leukemia (CML) is monitored by quantification of BCR::ABL1 transcript levels." (PMID 37875583, 2023). "Chronic myeloid leukemia (CML) is the outcome of constitutive tyrosine kinase BCR-Abl enzyme activity, the product of the bcr-abl gene fusion present in the Philadelphia chromosomes of patients whom suffer from CML." (PMID 36838629, 2023). "Reverse transcriptases (RT) are essential tools in BCR::ABL1 fusion transcript monitoring in chronic myeloid leukemia (CML)." (PMID 37568730, 2023). "In the case of chronic myelogenous leukemia (CML) the BCR-ABL fusion initiates chronic phase disease with second hits allowing progression to blast crisis." (PMID 38234720, 2023). "The patient was diagnosed with chronic myeloid leukemia by bone marrow biopsy, BCR::ABL1 fusion gene testing, and Philadelphia chromosome." (PMID 38031195, 2023). "Chronic myeloid leukemia (CML) is a hematological malignancy, of which approximately 90% are caused by BCR-ABL." (PMID 36854750, 2023). "Chronic myeloid leukemia (CML) is a clonal myeloproliferative disease characterized by the presence of the BCR-ABL fusion gene, which results from the Philadelphia chromosome." (PMID 38068992, 2023). "Chronic myeloid leukemia (CML) results from BCR-ABL oncogene, which blocks CML cells differentiation and protects these cells from apoptosis." (PMID 37215441, 2023). "Examples include tyrosine kinase inhibitors (TKI) in chronic myelogenous leukemia (CML) that block BCR::ABL1 kinase activity and differentiation therapy with all-trans retinoic acid (ATRA) in acute promyelocytic leukemia (APL) targeting the (PML::RARA) fusion." (PMID 37699001, 2023). "A fusion oncogene known as BCR:: ABL1, was one of the first diagnostic translocations found in patients with chronic myeloid leukemia (CML) in the 1980s." (PMID 36902091, 2023). "Chronic myeloid leukaemia (CML) is a clonal haematopoietic malignancy in which the formation of BCR-ABL fusion proteins is the most distinctive feature." (PMID 37875983, 2023). "Although the development of BCR::ABL1 tyrosine kinase inhibitors (TKIs) rendered chronic myeloid leukemia (CML) a manageable condition, acquisition of drug resistance during blast phase (BP) progression remains a critical challenge." (PMID 37932786, 2023). "Today, we celebrate two decades of experience with imatinib and later-generation BCR::ABL1 tyrosine kinase inhibitors (TKIs) in Philadelphia chromosome (Ph)-positive chronic myeloid leukemia (CML)." (PMID 37088793, 2023). "The discovery of the BCR–ABL fusion protein in patients with chronic myeloid leukemia (CML) marked the inception of a new era in cancer research." (PMID 37375228, 2023). "Chronic Myeloid Leukemia (CML) is a commonly occurring hematological neoplasm, in adults, caused by BCR::ABL1 gene mutation in the myeloid cells." (PMID 38188307, 2023). "Two main groups of MPN, BCR::ABL1-positive (Chronic Myeloid Leukemia) and BCR::ABL1-negative (Polycythemia Vera, Essential Thrombocytosis, Primary Myelofibrosis) are distinguished." (PMID 36980287, 2023). "Imatinib is a very potent inhibitor of tyrosine kinases such as ABL kinase, chimeric oncoprotein BCR-ABL of chronic myeloid leukemia, transmembrane KIT receptors, PDGFRα, and PDGFRb." (PMID 37623504, 2023). "Following the exploitation of BCR/ABL kinase inhibition in chronic myeloid leukaemia, efforts have been made to explore PP2A phosphatase reactivation/inhibition in anti-tumour therapy." (PMID 34728792, 2022). "The most recent two decades have seen tremendous progress in the understanding and treatment of chronic myeloid leukemia, a disease defined by the characteristic Philadelphia chromosome and the ensuing BCR::ABL fusion protein." (PMID 35626137, 2022).
chronic myeloid leukemia (continued). "Breast cancer cells show high levels of LASP1 phosphorylated at S146 by PKA, while in chronic myeloid leukemia (CML) cells a dominant phosphorylation of LASP1 at Y171 by the constitutively active BCR-ABL tyrosine kinase was observed." (PMID 36497077, 2022). "Chronic myeloid leukemia (CML) is characterized by the BCR::ABL1 gene fusion, which codes for a constitutively active tyrosine kinase." (PMID 35902731, 2022). "Chronic myeloid leukemia (CML) is a hematological malignancy that results when HSCs acquire the fusion oncogene BCR-ABL, leading to constitutive activation of the ABL tyrosine kinase." (PMID 36091167, 2022). "In this study, we investigated the mechanisms of COL-3-induced cytotoxicity in a chronic myeloid leukemia cell line, K562, characterized by the BCR–ABL fusion protein." (PMID 35055357, 2022). "Chronic myeloid leukemia is a disease diagnosed by the presence of the Philadelphia chromosome, which leads to the BCR::ABL fusion oncoprotein and overactive tyrosine kinase activity." (PMID 35626137, 2022). "Imatinib is a first-line therapy for chronic myeloid leukemia (CML), a form of cancer caused by chromosomal fusion of BCR and ABL1." (PMID 36090793, 2022). "Chronic myelogenous leukemia (CML) which is resulted from the BCR-ABL tyrosine kinase (TK) chimeric oncoprotein, is a malignant clonal disorder of hematopoietic stem cells." (PMID 36522400, 2022). "BCR::ABL1 is the primary driver of chronic myeloid leukaemia (CML) but this chimeric gene exists in several different isoforms that need to be recognized for optimal patient management." (PMID 35676453, 2022). "Standardized monitoring of BCR::ABL1 mRNA levels is essential for the management of chronic myeloid leukemia (CML) patients." (PMID 35614319, 2022). "The oncogenic BCR-ABL fusion protein drives some chronic myeloid leukemias (CML) and represents an important target for treatment." (PMID 35879309, 2022). "Tyrosine kinase inhibitors (TKIs) targeting BCR::ABL1 have turned chronic myeloid leukaemia (CML) from a fatal disease into a manageable condition for most patients." (PMID 36536477, 2022). "Chronic myeloid leukemia (CML) is characterized by clonal myeloproliferation arising from transformed HSCs presenting the chimeric oncogene BCR-ABL." (PMID 36291856, 2022). "Chronic myelogenous leukemia is characterized by presence of the BCR:ABL1 fusion and treated using imatinib mesylate (Gleevec)." (PMID 35625354, 2022). "Chronic myeloid leukemia (CML) is a BCR::ABL1-positive MPN, characterized by leukocytosis due to proliferation of mainly the granulocytic lineage." (PMID 35819517, 2022). "Other leukemias associated with CCR7 include chronic myelogenous leukemia (CML), which is characterized by the presence of the Philadelphia chromosome containing the BCR-ABL fusion gene." (PMID 35203305, 2022). "Second, in chronic myeloid leukemia, c-Abl is constitutively active due to its fusion with breakpoint cluster region protein (BCR), promoting DNA repair." (PMID 34616682, 2021). "Imatinib is a small molecule inhibitor of the constitutively active fusion BCR-ABL kinase which is present in more than 90% of chronic myeloid leukaemia (CML) cases and 30% of B-cell acute lymphoblastic leukaemia cases." (PMID 35008867, 2021). "Chronic myeloid leukemia (CML) is caused by the development of the Philadelphia (Ph) chromosome; the resulting fusion gene encodes the BCR-ABL chimeric protein, which has stronger kinase activity than ABL." (PMID 34771576, 2021). "Chronic myelogenous leukemia (CML) is a clonal malignancy of hematopoietic stem cells featured with the fusion protein kinase BCR-ABL." (PMID 33963175, 2021). "In chronic myeloid leukemia, the identification of BCR-ABL fusion gene, which leads to overproduction of a growth-stimulatory tyrosine kinase, led to the development of targeted TKIs with imatinib targeting BCR-ABL as the first." (PMID 34988471, 2021).
chronic myeloid leukemia (continued). "The BCR-ABL fusion gene plays a crucial role in the leukemogenesis of chronic myeloid leukemia (CML)." (PMID 34346842, 2021). "Chronic myeloid leukemia (CML) treatment depends on the administration of continuous BCR-ABL tyrosine kinase inhibitors (TKIs)." (PMID 33705648, 2021). "All compounds were evaluated for their inhibitory activities against a chronic myeloid leukemia cell line (K562) that expresses the enzyme tyrosine kinase BCR-Abl-1 and against healthy cells (WSS-1) to observe their selectivity." (PMID 34621389, 2021). "Depending on breakpoints of rearrangement different types of BCR–ABL fusion protein can be generated in patients of chronic myeloid leukemia (CML)." (PMID 34183996, 2021). "BAY-293, an inhibitor of SOS1/Ras, was found to depress proliferation and colony formation in chronic myeloid leukemia cells with resistance and BCR-ABL independence." (PMID 34938856, 2021). "On the other hand, the pathological effect of oncogene transfer by EVs was demonstrated by an in vivo study showing that the BCR/ABL fusion gene transferred by exosomes derived from K562 cells induces chronic myeloid leukemia in immunodeficient mice." (PMID 34200790, 2021). "Knockout of 5‐LO in BCR/ABL transduced bone marrow cells completely prevented the development of chronic myeloid leukemia in mice." (PMID 33205517, 2021). "The fusion protein BCR/ABL in the Philadelphia chromosome is characteristic of predominantly chronic myeloid leukemia (CML) and acute lymphoblastic leukemia (ALL)." (PMID 34777681, 2021). "Chronic myeloid leukemia (CML) is a myeloproliferative neoplasm driven by a fusion gene, encoding for the chimeric protein BCR-ABL, with constitutive tyrosine kinase activity." (PMID 34290617, 2021). "The constitutively active tyrosine-kinase BCR/ABL1 oncogene plays a key role in human chronic myeloid leukemia development and disease maintenance, and determines most of the features of this leukemia." (PMID 33557401, 2021). "Fusion genes resulting from chromosomal rearrangements are frequently found in various cancer cells, such as the breakpoint cluster region (BCR)-c-abl oncogene 1 (ABL) in chronic myeloid leukemia (CML)." (PMID 34249948, 2021). "On the other hand, administration of galectin-9 increases the sensitivity of chronic myeloid leukemia to the BCR-ABL tyrosine kinase drug imatinib." (PMID 34572756, 2021). "Previous studies have reported that HSPA8 can promote BCR/ABL-induced chronic myeloid leukemia cells’ survival." (PMID 33926391, 2021). "ABL1 presents at 9q34.12 on chromosome 9, translocate with the breakpoint cluster region (BCR) gene on chromosome 22 to form the Philadelphia chromosome, the cause of chronic myelogenous leukemia." (PMID 33952249, 2021). "Chronic myelogenous leukemia (CML) is caused by a gene translocation of BCR and ABL genes resulting in the fusion oncogene BCR-ABL." (PMID 33297302, 2020). "Chronic myeloid leukemia (CML) is a hematopoietic stem cell disorder caused by a reciprocal translocation between chromosomes 9 and 22, resulting in the BCR-ABL fusion gene." (PMID 32373501, 2020). "We next tested imatinib that primarily targets the PDGFR signaling, which was approved for treating chronic myeloid leukemia by targeting BCR/ABL and treating gastrointestinal stromal tumor." (PMID 32709869, 2020). "Historically, one of the most important targets in malignant hematology is the fusion protein BCR-ABL in chronic myeloid leukemia (CML)." (PMID 32911829, 2020). "This initialized with the discovery of a small-molecule kinase inhibitor specifically targeted to the mutant BCR-ABL protein present in the tumor cells of patients with chronic myeloid leukemia (CML)." (PMID 32759789, 2020). "Since the original identification of the Philadelphia chromosome in 1959 and the subsequent discovery of the BCR:ABL fusion in chronic myelogenous leukemia, significant efforts have been aimed at identifying the causative genes driving cancer pathogenesis." (PMID 32235397, 2020).
chronic myeloid leukemia (continued). "The aim of this study was analyzing the BCR-ABL transcript types of patients with chronic myeloid leukemia (CML) in Dr Sardjito General Hospital, Yogyakarta, Indonesia." (PMID 32592347, 2020). "The dCas9‐AID was stably expressed in K562 cells, a chronic myelogenous leukaemia (CML) line that contains the BCR‐ABL oncogene and is sensitive to imatinib." (PMID 31365173, 2020). "Autophagy is a critical mechanism of the anti-leukemic effects of ATO and contributes to the ATO-induced degradation of fusion oncoproteins such as PML-RARA in APL cells and BCR-ABL in chronic myelocytic leukemia (CML) cells 8-11." (PMID 32284743, 2020). "Chronic myeloid leukemia (CML) pathogenesis is mainly driven by the oncogenic breakpoint cluster region-Abelson murine leukemia viral oncogene homolog 1 (BCR-ABL) fusion protein." (PMID 32430012, 2020). "Breakpoint cluster region‐Abelson murine leukemia (BCR‐ABL) inhibitors markedly improve the prognosis of chronic myeloid leukemia." (PMID 30561126, 2019). "Several chromosome rearrangements are specific of a particular disease, such as the translocation between chromosomes 9 and 22 in chronic myeloid leukaemia (known as the ‘Philadelphia’ chromosome), yielding the BCR-ABL fusion protein." (PMID 31547595, 2019). "Chronic myelogenous leukemia (CML) is characterized by the BCR-ABL fusion protein with constitutive kinase activity." (PMID 31527518, 2019). "The BCR-ABLp190, LMO2, and BCR-ABLp210 oncogenes play a role in human B-lymphocyte, acute T-lymphoblastic, and chronic myeloid leukaemia, respectively." (PMID 31861691, 2019). "The proof of this concept has been provided by the remarkable antitumour activity of the small BCR (breakpoint cluster region)-ABL (Abelson) TK inhibitor imatinib in chronic myeloid leukaemia (CML)." (PMID 31091767, 2019). "Chronic myelogenous leukemia (CML) is a myeloproliferative neoplasm that arises from the acquisition of constitutively active BCR‐ABL tyrosine kinase in hematopoietic stem cells." (PMID 31373443, 2019). "Chronic myeloid leukemia (CML) is a myeloproliferative neoplasm characterized by the presence of BCR‐ABL fusion gene (GenBank accession NC_000022.11)." (PMID 31206255, 2019). "Using this knowledge-driven approach, the targeting of oncogenic alterations, such as the gene rearrangement BCR-ABL in chronic myelogenous leukemia (CML), ushered in the current era of “precision medicine” and “targeted therapy”." (PMID 31426419, 2019). "Chronic myeloid leukemia (CML) is a myeloproliferative neoplasm due to the engagement of an aberrant onco-protein BCR-ABL." (PMID 31683978, 2019). "The broadest classification is by BCR-ABL (Philadelphia chromosome) positive status for chronic myeloid leukemia (CML)." (PMID 31126326, 2019). "The lowest reported subtypes were chronic myelogenous leukemia, BCR/ABL positive (0.6%) in the southern region and also leukemia, NOS (0.7%) in the Central region of the country." (PMID 31315607, 2019). "For example, with chronic myeloid leukemia, demonstration of the BCR-ABL fusion gene or the Philadelphia chromosome by FISH, PCR, or cytogenetics in the presence of characteristic clinical findings (splenomegaly, leukocytosis) defines the disease." (PMID 30442928, 2018). "Chronic myeloid leukaemia (CML) is a myeloproliferative disorder, linked with a constitutively active tyrosine kinase BCR-ABL." (PMID 29670043, 2018). "The majority of cases of childhood chronic myelogenous leukemia cases are characterized by the expression of the breakpoint cluster region/Abelson (BCR/ABL) fusion gene, which is a product of the Philadelphia (Ph) chromosome." (PMID 30407337, 2018). "This phenomenon has been observed in vitro or in vivo both in solid and in hematological disease models: BCR-ABL+ Chronic Myeloid Leukemia (CML), NPM-ALK+ Anaplastic Large Cell Lymphoma (ALCL), Gastric Cancer, Melanoma, Lung Cancer." (PMID 30545064, 2018).